OR10G4 (olfactory receptor family 10 subfamily G member 4)
Description:
Odorant receptor.
Synonyms: OR11-278
Tractability: Antibody: its Gene Ontology location is reachable by antibodies, with high confidence; UniProt places it where antibodies can reach, with medium confidence; UniProt predicts a signal peptide or a membrane-spanning region.
Gene: Protein-coding gene on chromosome 11 (124,012,997 to 124,018,732, forward strand). Ensembl gene ENSG00000254737.
Subcellular location: Cell membrane
Pathways (Reactome):
Sensory Perception: Expression and translocation of olfactory receptors; Olfactory Signaling Pathway
Gene Ontology:
Molecular function: protein binding; olfactory receptor activity; G protein-coupled receptor activity
Biological process: detection of chemical stimulus involved in sensory perception of smell; G protein-coupled receptor signaling pathway
Cellular component: plasma membrane; membrane
Genetic constraint (gnomAD): Loss-of-function variants: 0 observed, 0.38 expected, observed/expected ratio (o/e) 0, 90% interval 0 to 1.85. That is too few expected variants to judge how well the gene tolerates losing a copy. Missense variants: 318 observed, 375.2 expected, observed/expected ratio (o/e) 0.85, 90% interval 0.77 to 0.93. Synonymous variants: 130 observed, 151.52 expected, observed/expected ratio (o/e) 0.86, 90% interval 0.74 to 0.99.
Homologues: Orthologues: macaque OR10G9 (91% identical), dog OR10G9C (86% identical), mouse Or10g9 (86% identical), rat Or10g9 (86% identical), dog OR10G9 (85% identical), mouse Or10g9b (85% identical), mouse Or10g7 (85% identical), rat Or10g9b (84% identical). Paralogues in human: OR10G9 (94% identical), OR10G7 (89% identical), OR10G8 (87% identical), OR10G2 (57% identical), OR10G6 (54% identical), OR10G3 (53% identical), OR10D3 (52% identical), OR10S1 (52% identical), OR2F1 (45% identical), OR2F2 (45% identical), OR10A7 (44% identical), OR2D3 (44% identical), and 80 more.